THUMPD2 (THUMP domain 2 tRNA and snRNA guanosine methyltransferase)
Description:
Catalytic subunit of the THUMPD2-TRM112 methyltransferase complex, that specifically mediates the S-adenosyl-L-methionine-dependent N(2)-methylation of guanosine nucleotides, most probably at position 72 (m2G72), in the U6snRNA of the major spliceosome. This modification in the U6 snRNA affects the constitutive splicing efficiency of introns that have suboptimal splice sites and can impact final mRNA levels.
Synonyms: C2orf8; MGC2454
Tractability: PROTAC: ubiquitination databases record sites on it.
Gene: Protein-coding gene on chromosome 2 (39,736,060 to 39,779,276, reverse strand). Ensembl gene ENSG00000138050.
Subcellular location: Nucleus
Subcellular location (Human Protein Atlas): Nucleoplasm
Gene Ontology:
Molecular function: protein binding; U6 snRNA (guanine-N(2))-methyltransferase activity; tRNA (guanine) methyltransferase activity; RNA binding; snRNA methyltransferase activity
Biological process: regulation of alternative mRNA splicing, via spliceosome; RNA methylation; tRNA methylation
Cellular component: methyltransferase complex; nucleus; tRNA methyltransferase complex
Genetic constraint (gnomAD): Loss-of-function variants: 38 observed, 35.68 expected, observed/expected ratio (o/e) 1.07, 90% interval 0.82 to 1.4. The upper end of that interval is the gene's LOEUF score, 1.4, which puts it in group 5 of 6, group 1 being the genes least tolerant of losing a copy. Missense variants: 610 observed, 498.23 expected, observed/expected ratio (o/e) 1.22, 90% interval 1.14 to 1.31. Synonymous variants: 204 observed, 171.46 expected, observed/expected ratio (o/e) 1.19, 90% interval 1.06 to 1.34.
Homologues: Orthologues: chimpanzee THUMPD2 (99% identical), macaque THUMPD2 (95% identical), dog THUMPD2 (82% identical), rabbit THUMPD2 (78% identical), guinea pig THUMPD2 (73% identical), pig THUMPD2 (73% identical), mouse Thumpd2 (69% identical), rat Thumpd2 (66% identical), tropical clawed frog thumpd2 (42% identical), zebrafish thumpd2 (33% identical), Caenorhabditis elegans M04B2.2 (18% identical). Paralogues in human: THUMPD3 (22% identical).
Diseases named in the same sentence as THUMPD2 in open-access papers:
THUMPD2 is named in the same sentence as 13 diseases in open-access papers, as found by Europe PMC text mining. Sharing a sentence is not in itself a finding about the gene and the disease. The quoted sentences say what the papers report.
age-related macular degeneration (1 paper, 2021). Age-related loss of vision in the central portion of the retina (macula), secondary to retinal degeneration. "Third, a rare indel, rs557998486, located near the THUMPD2 gene, is associated with age-related macular degeneration (MAF = 0.009, OR = 10.5, p = 2.75 × 10−8)." (PMID 33893285, 2021).
macular degeneration (1 paper, 2021). Loss of vision in the central portion of the retina (macula), secondary to retinal degeneration. "We also sought replication of the recessive association of rs557998486 near THUMPD2 gene with macular degeneration in FinnGen." (PMID 33893285, 2021).
cancer (1 paper, 2024). A tumor composed of atypical neoplastic, often pleomorphic cells that invade other tissues. "The functional significance of TRMT11/THUMPD2/THUMPD3-mediated tRNA m2G modifications in cancer cells remains largely unexplored compared to extensively investigated modifications such as m7G and m5C." (PMID 39019857, 2024). "Therefore, further validation is required to ascertain the involvement of TRMT112 and TRMT11/THUMPD2/THUMPD3 in the proliferation of diverse cancer cells." (PMID 39019857, 2024).
THUMPD2 also shares sentences with these, for which no sentence is quoted: depression (2 papers); bipolar depression (1); breast carcinoma (1); cardiovascular disease (1); ovarian carcinoma (1); pancreatic cancers (1); psychiatric disorder (1); schizophrenia (1); tumor (1); type 2 diabetes (1).